RNU7-186P (RNA, U7 small nuclear 186 pseudogene)
Gene: Small nuclear RNA gene on chromosome 17 (47,259,358 to 47,259,420, reverse strand). Ensembl gene ENSG00000238419.
Homologues: Orthologues: macaque U7 (94% identical). Paralogues in human: RNU7-14P (84% identical), RNU7-21P (83% identical), RNU7-34P (83% identical), RNU7-27P (81% identical), RNU7-61P (81% identical), RNU7-7P (81% identical), RNU7-106P (79% identical), RNU7-18P (79% identical), RNU7-23P (79% identical), RNU7-28P (79% identical), RNU7-3P (79% identical), RNU7-40P (79% identical), and 141 more.